PLXND1 (plexin D1)
Description:
Cell surface receptor for SEMA4A and for class 3 semaphorins, such as SEMA3A, SEMA3C and SEMA3E. Plays an important role in cell-cell signaling, and in regulating the migration of a wide spectrum of cell types. Regulates the migration of thymocytes in the medulla. Regulates endothelial cell migration. Plays an important role in ensuring the specificity of synapse formation. Required for normal development of the heart and vasculature (By similarity). Mediates anti-angiogenic signaling in response to SEMA3E.
Synonyms: KIAA0620; CHTD9; PLEXD1
Tractability: Small molecule: a structure with a bound ligand is known. Antibody: its Gene Ontology location is reachable by antibodies, with high confidence; UniProt places it where antibodies can reach, with medium confidence; UniProt predicts a signal peptide or a membrane-spanning region. PROTAC: ubiquitination databases record sites on it; its protein half-life has been measured.
Gene: Protein-coding gene on chromosome 3 (129,555,213 to 129,606,681, reverse strand). Ensembl gene ENSG00000004399.
Subcellular location: Cell membrane; Cell projection, lamellipodium membrane
Pathways (Reactome):
Signal Transduction: NOTCH3 Intracellular Domain Regulates Transcription; RND2 GTPase cycle
Developmental Biology: Other semaphorin interactions
Gene Ontology:
Molecular function: protein binding; protein domain specific binding; semaphorin receptor activity
Biological process: angiogenesis; endothelial cell migration; negative regulation of cell adhesion; outflow tract morphogenesis; positive regulation of axonogenesis; regulation of angiogenesis; regulation of cell migration; regulation of cell shape; semaphorin-plexin signaling pathway; synapse assembly; negative regulation of neuron apoptotic process; synaptic target recognition
Cellular component: lamellipodium; plasma membrane; semaphorin receptor complex; axon; cell body; glutamatergic synapse; lamellipodium membrane; plasma membrane bounded cell projection
Genetic constraint (gnomAD): Loss-of-function variants: 50 observed, 157.95 expected, observed/expected ratio (o/e) 0.32, 90% interval 0.25 to 0.4. The upper end of that interval is the gene's LOEUF score, 0.4, which puts it in group 1 of 6, group 1 being the genes least tolerant of losing a copy. Missense variants: 2,027 observed, 2,389.4 expected, observed/expected ratio (o/e) 0.85, 90% interval 0.82 to 0.88. Synonymous variants: 1,121 observed, 1,017.7 expected, observed/expected ratio (o/e) 1.1, 90% interval 1.05 to 1.16.
Homologues: Orthologues: chimpanzee PLXND1 (99% identical), macaque PLXND1 (98% identical), dog PLXND1 (94% identical), pig PLXND1 (93% identical), mouse Plxnd1 (91% identical), rat Plxnd1 (91% identical), rabbit PLXND1 (86% identical), guinea pig PLXND1 (71% identical), tropical clawed frog plxnd1 (63% identical), Drosophila melanogaster PlexA (30% identical), Drosophila melanogaster PlexB (30% identical), Caenorhabditis elegans plx-1 (27% identical), and 1 more. Paralogues in human: PLXNB1 (34% identical), PLXNB3 (34% identical), PLXNB2 (33% identical), PLXNA1 (32% identical), PLXNA2 (32% identical), PLXNA4 (31% identical), PLXNA3 (31% identical), PLXNC1 (26% identical).
Diseases named in the same sentence as PLXND1 in open-access papers:
PLXND1 is named in the same sentence as 82 diseases in open-access papers, as found by Europe PMC text mining. Sharing a sentence is not in itself a finding about the gene and the disease. The quoted sentences say what the papers report.
breast cancer (6 papers, 2008 to 2024). A primary or metastatic malignant neoplasm involving the breast. "Suppression of such Sema-3E/Plexin-D1 signaling pathway in human and mouse breast cancer cells induced apoptosis in vitro and subsequently reduced metastasis in vivo." (PMID 29113093, 2017). "The Sema-3E/Plexin-D1 signaling promoted survival of breast cancer cells." (PMID 29113093, 2017). "Serving as a tumor suppressor, PLXND1 was reported to promote apoptosis in the absence of semaphorin 3E in breast cancer." (PMID 33489909, 2020). "Surprisingly, genes PLXNB1, B3, and D1 showed no significant differential expression in breast cancer tumors compared to normal, but PLXNB1 showed favorable prognosis, and PLXNB3 and PLXND1 showed poor prognosis for both OS and PFI." (PMID 32640719, 2020).
glioma (5 papers, 2019 to 2025). A benign or malignant brain and spinal cord tumor that arises from glial cells (astrocytes, oligodendrocytes, ependymal cells). "Previous work suggested that semaphorin 3C, plexin A2, plexin D1, and Nrp1 form a complex in glioma stem cells, whereas numerous studies have indicated the interaction of semaphorin 3A, plexins, and Nrp1." (PMID 34270956, 2021). "For example, SEMA3C mediates signalling via Plexin B1 in PCa whereas SEMA3C signals through Plexin D1 in glioma." (PMID 30759745, 2019). "For example, it was reported that the functional complex of SEMA3C with its receptors NRP1/PLXNA2/PLXND1 could activate Rac1/NF-κB signaling to promote the survival and migration of glioma stem-like cells." (PMID 32640719, 2020). "Furthermore, PLXND1 has been found to be a transcriptional target of the NOTCH signaling pathway, and BEX2 has been suggested as a tumor suppressor gene in glioma." (PMID 40788820, 2025). "The quantitative real-time PCR method was used to evaluate mRNA expression of SEMA3(A-G), neuropilins (NRP1 and NRP2), plexins (PLXNA2 and PLXND1), cadherins (CDH1 and CDH2), integrins (ITGB1, ITGB3, ITGA5, and ITGAV), VEGFA and KDR genes in 59 II-IV grade glioma tissues." (PMID 33036421, 2020).
melanoma (5 papers, 2009 to 2020). A malignant, usually aggressive tumor composed of atypical, neoplastic melanocytes. "Some studies have shown that PLXND1 was overexpressed in tumor cells and promoted tumor development and progression in several cancers, including colon cancers, melanoma, pancreatic cancer, and ovarian cancer." (PMID 33489909, 2020). "In fact, SEMA3E and its receptor PLXND1 was reported to promote tumor invasiveness and metastatic spreading of melanoma in mice, and SEMA3A was found to suppress tumor growth and metastasis in melanoma." (PMID 32640719, 2020). "Recently we demonstrated that Plexin D1 expression is correlated with tumor invasion level and metastasis in a human melanoma progression series." (PMID 19703316, 2009). "We recently demonstrated that PLXND1 expression is correlated with tumor invasion and metastasis in a human melanoma progression series." (PMID 19703316, 2009).
atherosclerosis (4 papers, 2021 to 2022). A disease characterized by the build-up of fatty material and calcium deposition in the arterial wall resulting in partial or complete occlusion of the arterial lumen. "In contrast, the Sema3E–Plexin-D1 signaling axis inhibits the proliferation and migration of vascular smooth muscle cells (VSMCs), which are hallmarks of atherosclerosis and restenosis." (PMID 35045890, 2022). "Once the bloodstream was disturbed, PLXND1 expression was upregulated, which promoted pro-inflammatory processes in atherosclerosis." (PMID 36017337, 2022). "The Sema3E–Plexin-D1 signaling axis promotes the development of atherosclerosis via the retention of inflammatory macrophages in the plaque." (PMID 35045890, 2022). "PLXND1 was recently shown to detect physical forces and translate them into intracellular biochemical signals in the context of atherosclerosis." (PMID 33837646, 2021). "Moreover, plexin D1 (PLXND1) is required for the response of endothelial cells to shear stress and regulates the site-specific distribution of atherosclerosis." (PMID 35404040, 2022). "Thus, the endothelial Plexin-D1–Nrp-1–VEGFR2 complex directly senses shear stress and regulates the site-specificity of atherosclerosis." (PMID 35045890, 2022).
pancreatic cancer (4 papers, 2020 to 2024). "In particular, SEMA3D, with its plexin D1 (PLXND1), has been linked with the invasion and dissemination of pancreatic cancer cells." (PMID 39766161, 2024). "Aside from chemokines, Semaphorin 3D (SEMA3D) from tumor cells activates Plexin D1 (PLXND1) on dorsal root ganglion (DRG) neurons to increase the migration and invasion activity of pancreatic cancer cells." (PMID 37347365, 2023). "This included elements of the Hedgehog signaling pathway (SHH, GAS1), semaphorin signaling (SEMA3A, PLXNA1, PLXNB2, PLXND1, PLXNA2, FARP1, FARP2) and also axon guidance pathways (ROBO1, SLIT1, SLIT3 and SLITRK2), all notable for their involvement in pancreatic cancer progression and metastasis." (PMID 36429078, 2022).
prostate carcinoma (4 papers, 2019 to 2024). A carcinoma that arises from epithelial cells of the prostate gland. "Association of PLXND1 with angiogenesis and cell migration is reported in cervical and prostate cancer respectively." (PMID 38627856, 2024). "High PLXND1 expression is associated with poorer prognosis in prostate cancer patients." (PMID 38585965, 2024).
systemic sclerosis (4 papers, 2015 to 2024). A chronic disorder, possibly autoimmune, marked by excessive production of collagen which results in hardening and thickening of body tissues. "It has also been shown that SEMA4A-Plexin-D1 contributed to the elevated IL-4 and IL-17 in patients with systemic sclerosis (SSc), and the same manner can be seen for other T CD4+ mediate diseases, including asthma, rheumatoid arthritis (RA), and multiple sclerosis (MS)." (PMID 38148815, 2024). "Emerging evidence suggests that mutations in PLXND1 or Semaphorin 3E, the canonical ligand of PLXND1, can lead to serious cardiovascular diseases, such as congenital heart defects, CHARGE syndrome and systemic sclerosis." (PMID 33837646, 2021). "The aim of the present study was to investigate whether in systemic sclerosis (SSc) Plexin-D1/Sema3E axis could be involved in the dysregulation of vascular tone control and angiogenesis." (PMID 26292963, 2015).
asthma (3 papers, 2022 to 2024). "In this study, we addressed the impact of PLXND1 deficiency in CD11c+ DC in an HDM allergic model of asthma." (PMID 39213301, 2024). "It is important, however, to verify that such Sema4A mutants lack binding to potentially asthma-upregulating Sema4A receptors such as ILT4 and Plexin D1." (PMID 35328445, 2022). "This study demonstrated that the absence of PLXND1 in CD11c+ DCs exacerbated bronchial hyperreactivity, including airway resistance (Rn) and tissue elastance (H)." (PMID 39213301, 2024). "The absence of PLXND1 skews the DC population towards a pro-inflammatory phenotype, contributing to exacerbated asthma features." (PMID 39213301, 2024).
glioblastoma (3 papers, 2009 to 2018). The most malignant astrocytic tumor (WHO grade IV). "Interestingly, by data mining in gene expression datasets, we found that—among other genes–PLXND1 levels were induced almost 4-fold upon constitutive Notch1 activation in glioblastoma stem cells." (PMID 27749937, 2016). "Hence, we screened a panel of cells lines representing renal cancer (CAKI‐1, CAKI‐2, ACHN), bladder cancer (UC13, T24), and glioblastoma (U87MG), for expression of SEMA3C, EGFR, MET, Plexin B1, Plexin D1, NRP1, and NRP2." (PMID 29348142, 2018).
Moebius syndrome (3 papers, 2021 to 2025). Moebius syndrome is a very rare congenital cranial dysinnervation disorder characterized by complete or incomplete facial paralysis in association with bilateral palsy of the abducens nerve causing impairment of ocular abduction. "A mutation within PLXND1 (c.2890G>A p.V964M) has been reported in a case of Poland–Moebius syndrome, a well-known association of classical MBS." (PMID 40362454, 2025). "De novo heterozygous missense PLXND1 variants were reported in three individuals with Moebius syndrome and variable dysmorphic features (including microcephaly, epicanthal folds, flat nasal bridge, micrognathia, external ear defects, dental defects, clinodactyly, and low-set thumbs)." (PMID 33827624, 2021). "Some links in the non-OMIM sources and supported by the older literature have been deemed not strong enough to deserve a separate entry in OMIM, e.g. the link between KCNJ8 and Cantú syndrome reported in DECIPHER or a link between PLXND1 and Moebius syndrome in Orphanet." (PMID 33836063, 2021).
Möbius syndrome (3 papers, 2015 to 2025). "It should nonetheless be of considerable interest to both clinical researchers and geneticists that our paper is the first to describe both Poland and Möbius syndrome in a patient with a mutation in the PLXND1 gene." (PMID 36581828, 2022). "Here, for the first time, we report a case of PMS associated with a novel mutation in the PLXND1 gene (NM_015103.3) and compare this with the mutations observed in the PLXND1 gene in isolated Möbius syndrome." (PMID 36581828, 2022). "While no genetic patterns have yet emerged to support PMS as a distinct entity, the PLXND1 gene at locus 3q21-22 has recently been implicated in a number of cases of isolated Möbius syndrome." (PMID 36581828, 2022). "A review of 14 additional cases with genetic data found no further evidence implicating PLXND1, though prior research has associated it with isolated Möbius syndrome." (PMID 40171366, 2025). "None implicated the PLXND1 gene which has previously been implicated in isolated Möbius syndrome." (PMID 36581828, 2022). "Taken in isolation, this suggests that while the missense variant in the PLXND1 gene is novel, its causal relationship to Mobius syndrome may not be strong." (PMID 36581828, 2022).
pulmonary fibrosis (3 papers, 2024 to 2025). Chronic progressive interstitial lung disorder characterized by the replacement of the lung tissue by connective tissue, leading to progressive dyspnea, respiratory failure, or right heart failure. "Utilizing siRNA targeting Plexin D1, we transfected primary human lung fibroblasts to assess its effects on pulmonary fibrosis." (PMID 40112179, 2025). "Moreover, inhibition of SEMA4A-Plexin-D1 reduced lung fibrosis mediated by AKT (protein kinase B) signaling." (PMID 38148815, 2024).
allergic asthma (2 papers, 2018 to 2024). A asthma with a basis in a pathological type I hypersensitivity reaction. "Using Sema-3E-deficient and Plexin-D1-deficient mouse models, respectively, we and others have previously revealed a critical immune regulatory role of Sema-3E/Plexin D1 in DC phenotypes and experimental allergic asthma." (PMID 29867980, 2018). "Our study highlights the significant role of PLXND1 in CD11c+ DC in the context of allergic asthma." (PMID 39213301, 2024).
allergic disease (2 papers, 2019 to 2024). An immune response that occurs following re-exposure to an innocuous antigen, and that requires the presence of existing antibodies against that antigen. "Although NeP patients with anti-plexin D1 antibodies have various underlying neurological diseases, they have common coexisting comorbidities, mainly allergic diseases, that enhance the production of autoantibodies." (PMID 31920952, 2019). "The common comorbidities in patients with anti-plexin D1 antibodies were allergic diseases and collagen diseases." (PMID 31920952, 2019).
astrocytoma (2 papers, 2009 to 2020). "In addition, two low grade astrocytomas showed infrequent vascular and tumor cell-associated PLXND1 expression." (PMID 19703316, 2009).
autoimmune disease (2 papers, 2021 to 2024). A disorder resulting from loss of function or tissue destruction of an organ or multiple organs, arising from humoral or cellular immune responses of the individual to their own tissue constituents. "Plexin D1 exhibited good diagnostic accuracy in differentiating DM patients from healthy controls (AUC of 0.75), as well as from patients with other autoimmune diseases (AUC of 0.78) and patients with DMD/BMD (AUC of 0.74) in the receiver operating characteristic analyses (ROC)." (PMID 38396646, 2024). "Moreover, CD9+ Plexin D1+ EVs did not correlate with the level of inflammatory markers (WBCs, platelets, and neutrophils) of other autoimmune diseases, namely, RA, SLE, and SSC." (PMID 38396646, 2024). "Eleven proteins (increased: ATP5B, CALML5, COLEC11, FCGBP, PLEK, PLXND1; decreased: APOB, ATP8B1, FAM20C, LOXL3, TIMD4) were significantly altered in bvFTD with autoimmune disease compared to those without autoimmune disease." (PMID 34539672, 2021).
colorectal cancer (2 papers, 2011 to 2019). A primary or metastatic malignant neoplasm that affects the colon or rectum. "By contrast, Sema3E/Plexin-D1 signaling in colorectal cancers increases cellular invasiveness and metastasis." (PMID 21559368, 2011).
epithelial ovarian cancer (2 papers, 2020 to 2024). "This investigation showcased a comprehensive genome-wide methylation profile of epithelial ovarian cancer (EOC) and identified six hypermethylated/downregulated genes, (POLR3B, PLXND1, GIGYF2, CRKL, STK4, and BMP2) as potential diagnostic targets." (PMID 38627856, 2024).
hemangioma (2 papers, 2019 to 2022). A benign vascular lesion characterized by the formation of capillary-sized or cavernous vascular channels. "Both inhibited the expression of the endothelial differentiation markers CD31, VE-cadherin, and the expression of the hemangioma endothelial markers NOTCH1, VEGFR1, and plexin D1 compared with the DMSO control (for P values)." (PMID 34874911, 2022). "Endothelial differentiation markers, CD31 and CDH5 and hemangioma endothelial markers NOTCH1, PLXND1 and VEGFR1 under each treatment condition in four biological replicates, determined by qPCR, were standardized as described." (PMID 31358114, 2019).
ischaemic stroke (2 papers, 2021 to 2022). "The underlying mechanism of Sema3E/Plexin-D1 signaling involvement in functional brain recovery after ischemic stroke is unclear." (PMID 33978913, 2022). "This study demonstrated that the reactivation of Sema3E-Plexin-D1 signaling following ischemic stroke is essential for reconstructing a healthy vasculature via the regulation of VEGF signaling during vascular remodeling." (PMID 33978913, 2022). "Because Sema3E-Plexin-D1 signaling is actively involved in many angiogenic conditions, we speculated that this signaling contributes to vascular remodeling after brain damage, such as in ischemic stroke." (PMID 33978913, 2022).
liver fibrosis (2 papers, 2025). "ITGA7, important for insulin and glucose metabolism, Taylor (2018) showed hypermethylation, as did PLXND1, a therapeutic target in liver fibrosis and associated with adipocyte lipolysis, further linking these epigenetic changes to the metabolic disruptions observed due to prenatal-BPA treatment." (PMID 40914344, 2025).
Obesity (2 papers, 2019 to 2024). Accumulation of substantial excess body fat. "Accordingly, inhibition of the Sema3E-Plexin D1 axis by vaccination may potentially be developed as a treatment for unhealthy obesity and diabetes." (PMID 30846754, 2019).